PRAP1 (proline rich acidic protein 1)
Description:
Lipid-binding protein which promotes lipid absorption by facilitating MTTP-mediated lipid transfer (mainly triglycerides and phospholipids) and MTTP-mediated apoB lipoprotein assembly and secretion (By similarity). Protects the gastrointestinal epithelium from irradiation-induced apoptosis (By similarity). May play an important role in maintaining normal growth homeostasis in epithelial cells. May down-regulate the expression of MAD1L1 and exert a suppressive role in mitotic spindle assembly checkpoint in hepatocellular carcinomas.
Synonyms: UPA; PRO1195
Tractability: Antibody: UniProt places it where antibodies can reach, with high confidence; UniProt predicts a signal peptide or a membrane-spanning region; its Gene Ontology location is reachable by antibodies, with medium confidence. PROTAC: a small molecule that binds it is known.
Gene: Protein-coding gene on chromosome 10 (133,347,196 to 133,354,013, forward strand). Ensembl gene ENSG00000165828.
Subcellular location: Secreted; Endoplasmic reticulum
Gene Ontology:
Molecular function: protein binding; triglyceride binding
Biological process: deactivation of mitotic spindle assembly checkpoint; DNA damage response; negative regulation of apoptotic process; cellular response to X-ray; positive regulation of intestinal lipid absorption; positive regulation of phospholipid transport; positive regulation of triglyceride transport
Cellular component: extracellular region; endoplasmic reticulum
Genetic constraint (gnomAD): Loss-of-function variants: 15 observed, 16.47 expected, observed/expected ratio (o/e) 0.91, 90% interval 0.61 to 1.4. The upper end of that interval is the gene's LOEUF score, 1.4, which puts it in group 5 of 6, group 1 being the genes least tolerant of losing a copy. Missense variants: 160 observed, 200.37 expected, observed/expected ratio (o/e) 0.8, 90% interval 0.7 to 0.91. Synonymous variants: 81 observed, 84.27 expected, observed/expected ratio (o/e) 0.96, 90% interval 0.8 to 1.16.
Homologues: Orthologues: macaque PRAP1 (76% identical), rat Prap1 (52% identical), guinea pig PRAP1 (51% identical), mouse Prap1 (46% identical).
Diseases named in the same sentence as PRAP1 in open-access papers:
PRAP1 is named in the same sentence as 15 diseases in open-access papers, as found by Europe PMC text mining. Sharing a sentence is not in itself a finding about the gene and the disease. The quoted sentences say what the papers report.
colorectal cancer (4 papers, 2019 to 2024). A primary or metastatic malignant neoplasm that affects the colon or rectum. "Therefore, PRAP1 is involved in MCC destruction-mediated cisplatin resistance in colorectal carcinoma." (PMID 37325046, 2023). "TCGA and GTEx data indicated high PRAP1 expression and low ZEB1 expression in colorectal cancer." (PMID 35978266, 2022). "Among these genes we observed CLIC3, PRAP1 and AHNAK2, which have been shown to promote cancer progression of gallbladder carcinoma, chemotherapeutic drug resistance in colorectal cancer and epithelial to mesenchymal transition in clear cell renal cell carcinoma, respectively." (PMID 30717152, 2019).
hepatocellular carcinoma (3 papers, 2021 to 2025). A malignant tumor that arises from hepatocytes. "PRAP‐1 is highly expressed in liver epithelial cells but downregulated in hepatocellular carcinoma." (PMID 40437817, 2025). "PRAP1 was a proline-rich acidic protein that could down-regulate MAD1 and inhibit mitotic checkpoint signaling in hepatocellular carcinoma." (PMID 34957220, 2021).
bladder cancer (2 papers, 2016 to 2023). "Here we aimed to assess the associations of nineteen polymorphisms from seven DNA repair–associated genes (PRAP1, OGG1, APEX1, MUTYH, XRCC1, XRCC2 and XRCC3) with bladder cancer and their interactions in the disease in a Han Chinese population." (PMID 27153553, 2016).
hypertriglyceridemia (2 papers, 2021 to 2023). A laboratory test result indicating elevated triglyceride concentration in the blood. "Deficiency of the Prap1 gene reduces hypertriglyceridemia, weight gain, and hepatic lipidosis in mice on an HFD." (PMID 37958806, 2023). "Last, PRAP1 deficiency or the E85V mutation diminishes hypertriglyceridemia, weight gain, and hepatosteatosis of mice on a HFD." (PMID 33168624, 2021).
Cerebral ischemia (1 paper, 2020). Restriction of arterial blood supply to the brain associated with insufficient oxygenation to support the metabolic requirements of the tissue. "In addition, we found that cerebral ischemia resulted in remarkably increased mRNA expression of interleukin (IL)-1β in both male and female mice, which were consistently reversed by PRAP-1 inhibition." (PMID 32317937, 2020).
heart failure (1 paper, 2023). Inability of the heart to pump blood at an adequate rate to meet tissue metabolic requirements. "To investigate whether SDSL is a biomarker for heart failure, we downregulated its expression and observed a decrease in the expression of Cleaved-PRAP1." (PMID 38250028, 2023). "However, compared to the ISO group, the promotion of myocardial cell apoptosis decreased, which suggests that SDSL may be a targeted biomarker for heart failure, as it can regulate PRAP1 and inhibit ISO-induced myocardial cell apoptosis." (PMID 38250028, 2023).
steatosis (1 paper, 2025). Increased lipid within the cytoplasm of cells. "Afamin (AFM), angiotensinogen (AGT), β-defensin 1 (DEFB1), and PRAP1 were correlated with steatosis; DEFB1 was correlated with the NAS; and 90 proteins were associated with hepatocyte ballooning." (PMID 40250425, 2025).
cancer (8 papers, 2019 to 2024). A tumor composed of atypical neoplastic, often pleomorphic cells that invade other tissues. "Adipose-derived exosomes can promote chemoresistance to oxaliplatin via transpotting exosomal microsomal triglyceride transfer protein (MTTP) into cancer cells and thus regulating PRAP1/ZNFE1/GPX4 signal pathway." (PMID 38737906, 2024). "Memory B cells are driven into this state by not only their own high expression of PRAP1 but also the influences of cancer cells via the MIF-CD74 axis." (PMID 35967424, 2022). "Strikingly, we observed that PRAP1 was significantly upregulated in memory B cells derived from cancer tissue." (PMID 35967424, 2022). "Given that the impairment of SAC formation gives rise to drug resistance, this finding implies that the interaction between PRAP1 and MAD1 may affect the chemotherapy resistance of cancer cells." (PMID 37325046, 2023).
tumor (7 papers, 2017 to 2025). "The tumor weight loss caused by drug treatment was lower due to PRAP1 overexpression (P<0.0001; P=0.0485) when compared with the cisplatin-treated control mice." (PMID 37325046, 2023). "In contrast, the expression of genes, including STAG3, GATA5, and CACNB2, which are associated with cell proliferation or tumorigenesis, and PRAP1, which is primarily involved in the inhibition of tumor cell apoptosis, increased in mouse KrasG12D/Galc KO pancreatic organoids." (PMID 37848935, 2023). "Up-regulation of the SPP1, miR-122, SRPX2, ADH1B, miR-21, SALL4 and PRAP1 genes, as well as down-regulation of miR-378e have been previously associated with an increased tumor cell migration capacity among sCRC, greater tumor progression potential, a metastatic phenotype and inhibition of apoptosis." (PMID 29296198, 2017). "Increased PRAP1 expression was also observed in the tumor tissues of patients with CRC when compared with that in paired adjacent normal tissues." (PMID 37325046, 2023). "Briefly, the tumor volume of the PRAP1-overexpression group treated with cisplatin was larger than that of the control group." (PMID 37325046, 2023). "Additionally, the tumor growth curve visually showed that mice injected with PRAP1-overexpressing HCT-116 cells developed resistance to cisplatin in comparison with the control group mice (P=0.0192; P=0.0006; P<0.0001)." (PMID 37325046, 2023). "Accordingly, PRAP1 is involved in the regulation of chemotherapy resistance in tumor cells." (PMID 37325046, 2023). "So, combination of both nanomaterial and the PRAP-1 inhibitor and labeling them by 99mTc and also the exploitation of the advantage of the active targeting of the nano-system to tumor cells give a high potential opportunity to have a novel potent drug that may start a new era in tumor theragnosis." (PMID 38072913, 2024). "Tumor-specific deep crypt secretory cells (tDCS, cluster 10) demonstrated elevated expression of TFF1, FABP1, CKB, PRAP1, IL32, GPRC5A, and SOD3, and were consistent with secretory lineage plasticity and immune or stress-associated signaling." (PMID 41282138, 2025). "A mouse tumor model was generated by the subcutaneous injection of control HCT-116 cells and PRAP1-overexpressed HCT-116 cells." (PMID 37325046, 2023). "We further investigated contexts of these spMOCA’s hub genes, where we identified specific prognostic genes serves as hub genes in the same tumor type, for example, WIPF2 and CASC3 for BRCA, COX6A1 and PRAP1 for CRC, E2F1 and AKR1C3 for LUSC, and TSPAN3 and SLC4A11 for OVCA." (PMID 41370198, 2025). "When compared with the control group (EGFP), there was no significant change in tumor growth in the PRAP1 overexpression group." (PMID 37325046, 2023). "In tumor tissues, Ki67-positive cells were moderately elevated (not significant) in the PRAP1-overexpression group when compared with those in control mice without drug treatment (P=0.0004; P=0.0002)." (PMID 37325046, 2023). "Mechanistically, PRAP1 positively regulate MAD1 expression, and the binding of MAD1 to MAD2 destroyed MCC assembly by weakening the interaction between MAD2 and BUBR1, which in turn allowed tumor cells to escape from the control of SAC." (PMID 37325046, 2023). "Bioinformatics analysis showed that TRIB3 and FABP1 may interact with CEACAM5, PRAP1, GABRP, and THBS4, and affect tumor immune microenvironment by regulating immune cells, and participate in the development and progression of GC." (PMID 34957220, 2021). "TRIB3 and FABP1 may interact with CEACAM5, PRAP1, GABRP and THBS4, and affect tumor immune microenvironment by regulating immune cells, and participate in the development and progression of GC." (PMID 34957220, 2021).
PRAP1 also shares sentences with these, for which no sentence is quoted: clear cell renal cell carcinoma (1 paper); gallbladder carcinoma (1); hepatic (1); lipidosis (1); migraine (1); Obesity (1).